S100A4 (S100 calcium binding protein A4)
Diseases named in the same sentence as S100A4 in open-access papers (continued):
Sharing a sentence is not in itself a finding about the gene and the disease.
colon adenocarcinoma (6 papers, 1999 to 2017). "S100A4 hypomethylation is also a feature of other cancers, including pancreatic and colon adenocarcinoma." (PMID 17579622, 2007). "The addition of 5-Aza-2′-deoxycytidine, an inhibitor of the eukaryotic DNA methyltransferase, induced the expression of the S100A4 gene in colon adenocarcinoma cell lines." (PMID 16265347, 2005). "Recently, in a separate study, S100A4 levels as detected by Western blotting, were found to be higher in seven of 12 colon adenocarcinoma specimens than in adjacent normal tissue." (PMID 11875708, 2002). "In agreement with our results, Takenaga (1999) showed that the expression of S100A4 in human colon adenocarcinoma cell lines was regulated by IFN-γ, but not influenced by IL-1, IL-6, various growth factors or IFN-α and -β." (PMID 12799648, 2003). "The present study demonstrates that interferon gamma (IFN-γ), but not IFN-α and IFN-β, down-regulates the S100A4 mRNA level in colon adenocarcinoma WiDr cells in time- and dose-dependent manners." (PMID 10389988, 1999).
pancreatic ductal adenocarcinoma (6 papers, 2010 to 2024). An infiltrating adenocarcinoma that arises from the epithelial cells of the pancreas. "S100A4 has emerged as a biomarker with predictive value for genetic subtypes, clinical phenotypes, and therapeutic strategies in pancreatic ductal adenocarcinoma." (PMID 38463521, 2024). "In 3 independent pancreatic ductal adenocarcinoma cohorts (total participants = 1184) the relationship between aberrant expression of prometastatic proteins S100A2 and S100A4 and survival was assessed." (PMID 32675551, 2020).
squamous cell carcinoma (6 papers, 2012 to 2025). A carcinoma arising from squamous epithelial cells. "On the other hand, S100A4 induction has also been shown to reduce motility and invasiveness, for example, in squamous cell carcinoma." (PMID 40853920, 2025). "Another compound, Amlexanox, has been shown to bind S100A4, S100A12 and S100A13 and to reduce proliferation of A431 epidermoid carcinoma cells by inhibiting S100A4 interaction with the Epidermal Growth Factor Receptor (EGFR)." (PMID 36232334, 2022). "Expression of FoxQ1 in adenocarcinoma was higher than in squamous cell carcinoma (P = 0.005), and high expression of FoxQ1 correlated with loss of E-cad expression (P = 0.012), and anomalous positivity of VIM (P = 0.024) and S100A4 (P = 0.004)." (PMID 22761930, 2012). "However, induction of S100A4 has also been shown to decrease motility and invasiveness, such as in squamous cell carcinoma, and down-regulation of S100A4 in astrocytes increased their migratory capacity in vitro." (PMID 22853000, 2012). "S100A4 induced ephrin-A1 mRNA and protein expression in adenocarcinoma, but not in squamous carcinoma cell lines, whereas the level of osteopontin was unaffected by S100A4 treatment." (PMID 22853000, 2012). "Interestingly, we observed that S100A4 was able to induce expression of ephrin-A1 both at the mRNA and protein level in adenocarcinoma, but not in squamous cell carcinoma cell lines." (PMID 22853000, 2012).
colitis (5 papers, 2015 to 2024). Inflammation of the colon. "S100A4+ macrophage-specific Smad4 deletion enhances colitis-associated tumorigenesis by promoting macrophage lipid metabolism-dependent M2 polarization, thereby revealing Smad4 in S1000A4+ macrophages as a potential prognostic marker for CRC patients." (PMID 39664586, 2024). "Our results revealed that S100A4+ cell-specific Smad4 deficiency aggravates the transformation of colitis into CRC by promoting the infiltration of macrophages and inflammatory factors." (PMID 39664586, 2024). "S100A4 is primarily expressed in intestinal macrophages, and promotes colonic inflammation and colitis-associated colon tumorigenesis." (PMID 39664586, 2024). "Smad4 deficiency in S100A4+ cells exacerbated DSS-induced colitis and promoted colorectal tumorigenesis." (PMID 39664586, 2024). "Animals adoptively transferred with S100a4Gfp/Gfp or S100a4+/+ CD45RBhigh CD4+ T cells developed equally colitis as assessed over time by the loss of body weight." (PMID 26734465, 2015). "However, it remains unclear whether Smad4 in S100A4+ cells affects colitis-associated carcinogenesis." (PMID 39664586, 2024). "Of particular interest, we noted that the gene S100A4 was common to both CRC immune cells (MP2) and IBD immune cells (MP2), contributing to colon inflammation and colitis-associated colon tumorigenesis." (PMID 38529274, 2024). "A histological assessment revealed a significant upregulation of S100A4 expression and down-regulation of Smad4 in both colitis and CRC tissues." (PMID 39664586, 2024). "Several reports have demonstrated that S100A4 enhanced colitis development by increasing the adherence of Citrobacter rodentium in intestinal epithelial cells." (PMID 38529274, 2024). "We found that S100A4+ cell-specific Smad4 deletion aggravated DSS-induced colitis and enhanced AOM/DSS-induced colitis-associated tumorigenesis." (PMID 39664586, 2024). "In this study, we demonstrated that S100A4 promotes colitis development via increasing the adherence of C. rodentium to intestinal epithelial cells." (PMID 28935867, 2017). "Here, in this study, we first demonstrated that S100A4 promotes bacteria-induced colitis, which elucidated a new mechanism of colitis pathology for C. rodentium." (PMID 28935867, 2017). "Infection-induced colitis, colonic pathology and inflammatory cell recruitment were also attenuated in S100A4−/−−/− mice." (PMID 28935867, 2017). "S100A4 also promotes colitis development via S100A4-mediated host inflammatory responses by increasing adhesion and colonization of Citrobacter rodentium." (PMID 29204268, 2017). "Smad4 expression in S100A4+ cells was also decreased in colitis and tumor tissues." (PMID 39664586, 2024). "Similarly, our results supported this conclusion and demonstrated that S100A4+ cell-specific Smad4 ablation aggravated colitis and CRC." (PMID 39664586, 2024). "Whether S100A4 influences C. rodentium-induced colitis was unknown." (PMID 28935867, 2017). "S100A4 may provide a promising strategy for treatment of colitis." (PMID 28935867, 2017). "A lack of S100A4 results in impaired inflammation and C. rodentium colonization and increased protection against C. rodentium induced colitis." (PMID 28935867, 2017).
colorectal adenocarcinoma (5 papers, 2000 to 2025). The most common type of colorectal carcinoma. "In the present study, S100A4 over-expression was observed in 52 (53.06%) of the 98 colorectal adenocarcinoma tissue specimens, correlating closely with factors indicative of tumor aggressiveness, such as lymph node metastasis, depth of invasion, and peritoneal dissemination." (PMID 39205741, 2024). "To study their involvement in the malignancy of human colorectal adenocarcinoma, we examined the protein expression levels of S100A6 and S100A4 in the primary colorectal adenocarcinoma (T) and paired adjacent normal colorectal mucosa (N) from 12 cases, quantitatively by Western blot analysis." (PMID 10952782, 2000). "S100A4, but not MYLK, BDNF, and PCOLCE2, exhibited higher expression in colorectal adenocarcinoma, but lower expression in normal colon tissues." (PMID 31581665, 2019).
diabetes (5 papers, 2013 to 2025). "One of the strengths of this study is the identification of three novel biomarkers for diabetes and kidney stones using machine learning methods: S100A4, ARPC1B, and CEBPD." (PMID 40718484, 2025). "Western blotting further confirmed that the protein levels of S100A4, ARPC1B, and CEBPD were significantly upregulated.These results collectively suggest that S100A4, ARPC1B, and CEBPD may serve as core biomarkers in the common mechanisms underlying diabetes and kidney stones." (PMID 40718484, 2025). "The mechanisms of S100A4, ARPC1B, and CEBPD in kidney stones and diabetes should be further explored in wet lab experiments." (PMID 40718484, 2025). "Among 101 machine learning models, S100A4, ARPC1B, and CEBPD were identified as the most significant interacting genes linking diabetes and kidney stones." (PMID 40718484, 2025). "PSMD3, a subunit of RNA polymerase, can induce the expression of Cox2, S100A4/FSP-1 and vimentin genes in renal, which contributes to diabetes-mediated chromatin turnover and promotes transcriptional changes in diabetic kidneys." (PMID 30521536, 2018). "Overall, our study suggests that S100A4, ARPC1B, and CEBPD may serve as valuable biomarkers that play a crucial role in the shared pathogenesis of kidney stones and diabetes." (PMID 40718484, 2025). "We identified three biomarkers—S100A4, ARPC1B, and CEBPD—that may play critical roles in the shared pathogenesis of diabetes and kidney stones." (PMID 40718484, 2025). "Several S100 members, mainly S100A4 and S100A8/9, have been identified as key players in the pathogenesis of many types of cancer, as well as of several other disease conditions, including diabetes and other inflammatory diseases." (PMID 39493128, 2024). "The S100a4 gene was upregulated in a previous study in the peripheral leukocytes of streptozotocin-induced diabetic rats, while the other 4 did not have changed expression levels due to diabetes." (PMID 24199937, 2013).
keloid (5 papers, 2016 to 2025). An irregularly shaped, elevated mark on the skin caused by deposits of excessive amounts of collagen during wound healing. "There was a higher fluorescence intensity of S100A4 in the keloid than in the normal skin, which meant accumulated fibroblast contributes to the pathogenesis of keloid." (PMID 36263010, 2022). "Such a result was consistent with our presumption that the hyper-m6A-modified highly expressed Wnt/β-catenin/S100A4 pathway played a role in the pathogenesis of keloid." (PMID 36263010, 2022). "Additionally, the Wnt and TGF-β pathways in keloids contained numerous high m6A level genes, and the Wnt/β-catenin/S100A4 pathway was elevated in human keloid samples, confirming Wnt signaling activation by m6A modification in keloids." (PMID 40860194, 2025). "Also, the modification of m6A methylation in the Wnt/β-catenin/S100A4 pathway remains unknown in keloid." (PMID 36263010, 2022). "Immunofluorescence revealed the presence of RSL3 in these grafts, alongside a reduction in S100A4+FTH1+ fibroblast cells and PLIN1+α-SMA+ adipocyte cells in keloid grafts following RSL3 therapy, consistent with in vitro experiments." (PMID 40860189, 2025). "The results showed that the expression of Wnt3a, β-catenin, and S100A4 proteins in keloid was significantly higher than that in normal skin (p < 0.05)." (PMID 36263010, 2022). "Moreover, the immunofluorescence staining result showed that S100A4 and WTAP were overlapped in the same cells in the keloid." (PMID 36263010, 2022).
Myocardial fibrosis (5 papers, 2021 to 2024). "Studies have found that S100A4 (fibroblast-specific protein 1) is associated with myocardial fibrosis after myocardial infarction and is regulated by Smad3 in myocardial interstitial fibroblasts, promoting myocardial fibrosis in the mouse model induced by pressure overload." (PMID 34484396, 2021). "S100A4 knockout can aggravate ventricular remodeling, myocardial fibrosis, and distal myocardial capillary density reduction in mice." (PMID 37118659, 2023). "This notion is supported by the documentation that downregulation of S100A4 through the Wnt/β-catenin pathway can alleviate myocardial fibrosis in mice." (PMID 37217870, 2023). "In addition, it has been shown that downregulation of S100A4 can reduce myocardial fibrosis in mice through the Wnt/β-catenin pathway, and knockdown of S100A4 can significantly reduce myocardial fibrosis and β-catenin levels." (PMID 35154161, 2022). "Therefore, attenuating myocardial fibrosis may provide therapeutic effects in heart failure and hypertrophy by blocking S100A4." (PMID 37217870, 2023).
myocardial infarction (5 papers, 2017 to 2024). Gross necrosis of the myocardium, as a result of interruption of the blood supply to the area, as in coronary thrombosis. "Serum S100A4 level was proposed as a novel biomarker for the detection of acute myocardial infarction." (PMID 37217870, 2023). "S100A4 expression protects against myocardial ischemia, supporting cardiac function after myocardial infarction." (PMID 37217870, 2023). "S100A4 mRNA level was elevated in different animal models of cardiac diseases such as acute afterload enhancement and acute myocardial infarction in rats and mice." (PMID 30283351, 2018). "The expression of S100A4 is low in the adult normal myocardium, but significantly enhanced in myocardial infarction, and the detection of plasma-S100A4 serves as a novel biomarker for acute myocardial infarction." (PMID 29204268, 2017). "However, in a murine model of myocardial infarction, the ablation of S100A4 results in augmented tissue remodeling and fibrosis, ultimately exacerbating cardiac functional deterioration." (PMID 38164183, 2024). "Increased steady-state concentration of S100A4 mRNA and protein levels have been found in pathologically hypertrophied and failing hearts of rats induced by aortic banding, myocardial infarction as well as TAC, or appropriate diet in Dahl salt-sensitive animals." (PMID 30283351, 2018). "Cardiac myocyte-specific overexpression of S100A4 after myocardial infarction may protect the infarcted myocardium against myocardial ischemia, while deletion of S100A4 increases cardiac damage." (PMID 29204268, 2017). "Moreover, in a murine model of myocardial infarction S100A4 KO mice showed more adverse fibrotic remodeling and post-ischemic damage, and this effect was attenuated upon reconstitution of S100A4 protein levels after adeno-associated virus serotype 9 (AAV9)-mediated overexpression of S100A4." (PMID 30283351, 2018). "Upon myocardial infarction induced by left anterior descending (LAD) coronary artery ligation, mice expressed higher amounts of S100A4." (PMID 30283351, 2018). "Finally, higher S100A4 protein levels were detected in human samples of hypertrophic cardiomyopathy (HCM) and acute myocardial infarction." (PMID 30283351, 2018).
systemic lupus erythematosus (5 papers, 2017 to 2022). An autoimmune multi-organ disease typically associated with vasculopathy and autoantibody production. "Increased urine levels of S100A4 have been reported in patients with a complex inflammatory autoimmune disease, childhood-onset systemic lupus erythematosus, indicating S100A4 role as a marker for lupus nephritis activity." (PMID 36235175, 2022). "We isolated Gr1highCD11b+ and Gr1lowCD11b+ cells from 9 week old male and female NZBWF1 lupus-prone mice and determined levels of S100a4, S100a8, and S100a9 mRNA." (PMID 34220829, 2021). "Similar to systemic lupus erythematosus, levels of S100A4 in plasma of axSpA patients are markedly lower compared to patients with RA." (PMID 32021963, 2020).
allergic dermatitis (4 papers, 2020 to 2025). "S100a4 -/- mice are protected from OVA-induced allergic dermatitis, characterized by reduced infiltration of eosinophils, T cells, neutrophils, and DCs at the challenge site, coupled with reduced serum OVA-specific antibodies and T cell memory responses." (PMID 40078995, 2025). "We clearly demonstrated the important contribution to the development of allergy by S100A4 using mouse models of allergic dermatitis and contact hypersensitivity." (PMID 34367151, 2021). "Refining the mouse model, especially using the S100a4-cre-recombinase transgenic mouse, provides tools to investigate autoinflammatory arthritis and atopic dermatitis." (PMID 32687504, 2020). "Moreover, S100A4 was over-expressed in the allergen-induced skin tissue of atopic dermatitis murine models, and the elevated S100A4 levels aggravated the Th2 inflammatory response." (PMID 36386522, 2022). "In a mouse model of allergic dermatitis, CD8 but not CD4 T cell infiltration at the rechallenge site was decreased in S100a4 -/- mice compared to WT controls." (PMID 40078995, 2025).
Allergy (4 papers, 2015 to 2022). An allergy is an immune response or reaction to substances that are usually not harmful. "In order to confirm the implication of S100A4 in mast cell activation in vivo, we assessed the intensities of PCA, a mast cell-dependent allergy model, in the WT and S100A4-/- mice." (PMID 34367151, 2021). "The calcium-binding protein S100A4 demonstrates important regulatory roles in many biological processes including tumorigenesis and inflammatory disorders such as allergy." (PMID 34367151, 2021). "We previously revealed a critical role of S100A4 in allergy, based on using systems biology and both clinical and experimental validation approaches." (PMID 34367151, 2021). "We have previously provided compelling evidence demonstrating a clear contribution of S100A4 to allergy and mucosal immune responses." (PMID 34367151, 2021). "We confirmed the impact of S100A4 on allergy using an experimental dermatitis model and a contact hypersensitivity model." (PMID 34367151, 2021). "Functional studies of human Th2 cells as well as mouse models of allergy showed that deletion of S100A4 resulted in decreased signs of allergy including Th2 cell activation, humoral immunity, and infiltration of effector cells." (PMID 26734465, 2015). "However, the specific mechanism of the contribution of S100A4 to allergic diseases awaits further clarification." (PMID 34367151, 2021). "Recently, we also identified a central role for S100A4 in allergy." (PMID 28951732, 2017). "The calcium-binding protein S100A4 has been described to promote pathological inflammation in experimental autoimmune and inflammatory disorders and in allergy and to contribute to antigen presentation and antibody response after parenteral immunization with an alum-adjuvanted antigen." (PMID 28951732, 2017).
biliary atresia (4 papers, 2010 to 2022). A rare, biliary tract disease characterized by progressive obliterative cholangiopathy of the intra- and extrahepatic bile ducts, occurring in the embryonic/ perinatal period, leading to severe and persistent neonatal jaundice and acholic stool. "Studies have shown that S100A4 is associated with pleural mesothelial cells and EMT in biliary atresia." (PMID 35154161, 2022).
colorectal tumors (4 papers, 2014 to 2025). "Among the IHC biomarkers expressed in colorectal tumors, FAP, α-SMA, VIM, S100A4, PDGFR-α/β, and POSTN were reported in a general review addressing the question of the significance of CAFs in tumor progression and metastasis." (PMID 41450913, 2025). "S100A4 and S100A6 play an important role in tumor metastases, including colorectal tumor metastasis." (PMID 36523772, 2022).
Crohn disease (4 papers, 2018 to 2022). A gastrointestinal disorder characterized by chronic inflammation involving all layers of the intestinal wall, noncaseating granulomas affecting the intestinal wall and regional lymph nodes, and transmural fibrosis. "Additionally, S100A4 promotes metastasis and is associated with intestinal fibroblast migration in patients with Crohn’s disease." (PMID 35657798, 2022). "Previous studies have reported a close association between S100A4 and the TGF-β signaling pathway in tumorigenesis and Crohn’s disease." (PMID 36078170, 2022).